SAMHD1 (SAM and HD domain containing deoxynucleoside triphosphate triphosphohydrolase 1)
Diseases named in the same sentence as SAMHD1 in open-access papers (continued):
Sharing a sentence is not in itself a finding about the gene and the disease.
cancer (continued). "Therefore, in conjunction with other gene KO mouse models targeting tumor suppressors, the SAMHD1-deficient mouse models provide an important tool to explore the potential role of SAMHD1 in cancer." (PMID 24257155, 2013). "Besides, similarly to RNR, although the direct catalytic activity of SAMHD1 may be responsible for the impact of its expression on cancer development, its participation in additional processes, such as DNA damage repair, may also be important." (PMID 39206868, 2024). "In a similar fashion, RNR inhibition leads to apparent indirect inactivation of SAMHD1 drug resistance activity, probably owing to imbalances in dNTP levels and perturbation of SAMHD1 allosteric regulation, highlighting their tight interconnection, which can be exploited for cancer therapy." (PMID 39206868, 2024). "Therefore, modulation of SAMHD1 activity by drugs or potentially through targeting of SAMHD1 for proteasomal degradation by the lentiviral accessory protein Vpx has been proposed as a strategy for improving anti-cancer and anti-HIV therapies." (PMID 38710701, 2024). "We assumed that SAMHD1 might function through multiple pathways in different types of cancer." (PMID 37009792, 2023). "Therefore, the roles of SAMHD1 in cancer are unclear and controversial." (PMID 37009792, 2023). "Based on these findings, we hypothesized that SAMHD1 regulates cell migration through epithelial–mesenchymal transition, a well-known mechanism by which cancer cells acquire mesenchymal characteristics and increase motility by losing cell–cell junctions and basal polarity." (PMID 37009792, 2023). "Furthermore, it will be important to dissect the influence of the dNTPase function of SAMHD1 on the effects observed in cancer cells, or whether additional functions contribute to tumorigenesis." (PMID 34480199, 2022). "However, as it yet remains to be clarified how T592 phosphorylation is connected to tetramerisation and dNTPase function, one can only speculate on the influence of SAMHD1 T592 phosphorylation on cancer cells." (PMID 34480199, 2022). "This could indicate that it is beneficial for cancers to maintain SAMHD1 phosphorylation." (PMID 34480199, 2022). "Collectively, our data confirm the key role of SAMHD1 in cancer progression but also indicates that its function might depend on the specific tumor type, being able to act as a tumor suppressor mainly for hematological tumors or alternatively as a promoter of cancer progression." (PMID 35158911, 2022). "SAMHD1 expression represents a new strong prognostic and predictive biomarker in solid tumors and, thus, modulation of the SAMHD1 function may constitute a promising target for the improvement of cancer therapy." (PMID 35158911, 2022). "All 230 coding mutations seem to distribute relatively evenly throughout the whole protein sequence of SAMHD1, which, at first glance, does not allow us to draw any conclusions on certain protein domains that might be important for cancer development." (PMID 34480199, 2022). "Therefore, SAMHD1 inhibition is considered a promising strategy to overcome tumor resistance and SAMHD1 expression has been proposed as a potential biomarker for the stratification of patients with cancer diagnosis that have to be treated with antimetabolites." (PMID 35158911, 2022). "Together with the unaltered cellular protein level of R366C and R366H, this significantly impaired hydrolysis activity suggests that alterations in the dNTPase activity of SAMHD1 may mechanistically involve the enzyme in the elevated dNTP pools observed in cancer cells." (PMID 34492268, 2021). "In addition to SAMHD1 expression defects, SAMHD1 alternations may also be involved in R-loop-mediated genome instability, and cancer development may be due to of its inability to interact with R-loop regulatory cofactors." (PMID 33857133, 2021).
cancer (continued). "Thus, pharmacological modulation of SAMHD1 activity has the potential to improve antiviral and anti-cancer therapies and paves the way to the identification of malignancies that may be treated with new drug combinations." (PMID 32197329, 2020). "One can imagine that a SAMHD1 nucleoside analog inhibitor might be useful in an anticancer regiment by promoting a dNTP imbalance in rapidly dividing cancer cells or in combination therapy with FDA-approved nucleoside analogs that are sensitive to hydrolysis by SAMHD1." (PMID 28046007, 2017). "Thus, SAMHD1 may play a key role in reducing random insertions by retroelements that contribute to genomic instability and lead to cancer development." (PMID 26416562, 2015). "It is unclear whether microRNA-181 downregulates SAMHD1 expression in cancer patients." (PMID 26416562, 2015). "Importantly, physiological significance and functional contributions of these SAMHD1 mutations to progression of cancer also needs to be investigated, especially since the SAMHD1 knockout in mice does not result in spontaneous tumorigenesis." (PMID 26416562, 2015). "Therefore, SAMHD1 can be placed at the crossroads of various cellular processes that may influence cancer cell biology via multiple dNTPase-dependent or -independent mechanisms, but the underlying mechanisms of SAMHD1 role in the induction and regulation of tumorigenesis remain unknown." (PMID 37667113, 2024). "This biochemical study of ZK177.8 protein supports its potentials as animal models for various SAMHD1-related human disorders (AGS, infectious diseases, and cancers) and cellular events such as cell proliferation and intracellular dNTP regulation." (PMID 37567474, 2023). "Consistent with the pattern of SAMHD1 expression, FAK phosphorylation levels were higher in cancer tissues than in normal tissues." (PMID 37009792, 2023). "Impairment of the noncatalytic replication fork restart function of SAMHD1 could promote replication stress in cancer cells, a hallmark of this disease and known to be a double‐edged sword, capable of promoting tumour progression but also being a tumour suppressive mechanism." (PMID 35583750, 2022). "However, SAMHD1′s role in cancer evolution is still unknown." (PMID 35158911, 2022). "The present review summarizes the negative role of SAMHD1 in chemotherapy sensitivity, highlights reported SAMHD1 mutations found in various cancer types, and aims to discuss functional consequences as well as underlying mechanisms of SAMHD1 dysregulation potentially involved in cancer development." (PMID 34480199, 2022). "Specifically, it will be important to investigate the consequences of SAMHD1 deregulation (whether it is due to mutations or mRNA/protein downregulation) for cellular dNTP metabolism, DNA replication, and/or DDR which is necessary to evaluate SAMHD1’s role in cancer development and progression." (PMID 34480199, 2022). "However, the mechanisms by which SAMHD1 preserves genomic integrity against intrinsic DNA damage and by which an endogenous source causes cancer development in SAMHD1-deficiency but not in other AGS-associated gene deficiencies remain unknown." (PMID 33857133, 2021). "We first screened the messenger RNA (mRNA) expression of the nucleotide degrading enzyme genes TREX1, SAMHD1, RNASEH2A, RNASEH2B, and RNASEH2C in 14 cancer types using TCGA RNAseq data." (PMID 29843367, 2018). "Here, we identified SAMHD1 acetylation, a novel PTM for this protein, and its roles in cancer cell proliferation." (PMID 28978134, 2017). "Therefore, SAMHD1 acetylation may be a potent therapeutic target for cancer treatment." (PMID 28978134, 2017). "Low (or no) expression of SAMHD1 was associated with a positive prognosis in breast, ovarian, and non-small cell lung cancer (NSCLC) cancer patients." (PMID 35158911, 2022). "Median DFS in NSCLC cancer patients was 22 months for SAMHD1 negative patients compared to 5 months for SAMHD1 positive patients (p = 0.009)." (PMID 35158911, 2022).
cancer (continued). "Accordingly, when we evaluated overall survival since cancer diagnosis (OSCD) patients with SAMHD1 positive tumors presented shorter OSCD than negative patients in all three cohorts." (PMID 35158911, 2022). "Several suggestions have been made to target SAMHD1 in order to improve nucleoside-based anti-cancer therapies, including treatment with Vpx to degrade SAMHD1 and treatment with RNR inhibitors to induce dNTP-pool imbalances and impede SAMHD1 allosteric activation." (PMID 35893688, 2022). "Two previously established CNDAC-adapted cancer cell lines had been shown to display reduced DCK levels but a contribution of SAMHD1 had not been investigated." (PMID 34641952, 2021). "Here, we evaluated how SAMHD1 function modifies the efficacy of a wide range of nucleoside and non-nucleoside antimetabolites currently used to treat cancer." (PMID 32197329, 2020). "Anti-HIV-1 activity of a panel of antimetabolite drugs used in cancer treatment was evaluated in MDMs in the presence or absence of SAMHD1, after transducing cells with HIV-2 Vpx." (PMID 32197329, 2020). "As ARD1 is reported to be oncogenic and the enzymatic activity of SAMHD1 is relevant to the cell cycle regulation, we hypothesized that ARD1-mediated SAMHD1 acetylation may contribute to cancer cell proliferation." (PMID 28978134, 2017). "Its primary physiological role is believed to be the maintenance of genome integrity by limiting the dNTP pool when DNA replication is not required, which is in keeping with observed SAMHD1 downregulation in several cancers." (PMID 28061811, 2017). "Data analyses based on multiple bioinformatics tools produced a large body of biologically meaningful information, and revealed a number of genes such as SAMHD1, G6PD, GPD2 and ENO1, which have been reported to be related to immune response, blood biology, bone remodeling, and cancer respectively." (PMID 27878450, 2017). "Nevertheless, the data show that removal of SAMHD1 activity in differentiated THP-1 cells by Vpx-mediated proteasomal degradation results in reduction of anti-HIV-1 activity of these anti-herpes and anti-cancer agents." (PMID 28220857, 2017). "Despite implications for epigenetic downregulation of SAMHD1 in cancer, the exact mechanisms are not known." (PMID 26416562, 2015). "Functional significance of SAMHD1 and its dNTPase activity in cancer pathophysiology has not yet been reviewed." (PMID 26416562, 2015). "Taken together, the findings suggest that SAMHD1 may be a potential prognostic biomarker in the adjuvant and neoadjuvant setting, and that the combination of cytotoxic chemotherapy and USP7 inhibition might improve chemotherapy sensitivity in various cancers." (PMID 37081042, 2023). "However, the dose-dependent Vpx-mediated SAMHD1 deficit and its effects have not yet been investigated in cancer cells, including GBM." (PMID 36139652, 2022). "Similarly, the noncatalytic role of SAMHD1 in DNA repair and replication fork restart, together with its links to the innate immune response, also has important implications for our understanding of cancer." (PMID 35583750, 2022). "Interestingly, SAMHD1 KO mice did not display an AGS phenotype and there is no report of cancer development in SAMHD1 KO mice, indicating that SAMHD1 functions may be species dependent." (PMID 34492268, 2021). "Interestingly, SAMHD1 putative cancer drivers are not found in any of the POLE-P286R tumours from a collection containing 2188 non-redundant samples from 10 colorectal and endometrial studies, suggesting that these mutations might be mutually exclusive." (PMID 34228709, 2021). "As small molecules failed to inhibit SAMHD1 in vitro, a novel approach was required to sensitize AML cancer cells and xenograft models to cytarabine." (PMID 35203388, 2022). "GID50 VLP(+Vpx)-mediated SAMHD1 depletion and CRISPR-mediated knockout resulted in an approximately 2-fold increase in the dNTP pool, comparable to non-GBM cancer cell line." (PMID 36139652, 2022).
cancer (continued). "Even though this decreasing trend in the amplified transcription of SAMHD1 at 24 h might result in loosening the regulation of CAD, DHODH and UMPS, the critical enzymes involved in direct influx of dTMP (TYMS and TYMP) did not appear to be recovered to normal levels in cancer cells." (PMID 36414668, 2022).
tumor (52 papers, 2013 to 2026). "The association of higher nuclear SAMHD1 with less advanced tumor stages and improved disease‐free survival highlights its potential as a long‐term therapeutic factor in HCC." (PMID 39679869, 2025). "Through proteomic analysis and drug screening, we identified a promising strategy for selectively depleting tumor-associated SAMHD1 while minimizing its impact on SAMHD1 expression in key normal cell types." (PMID 41392286, 2025). "Here, we report, for the first time, that STING activation is facilitated by SAMHD1 deficiency and further restricts tumor growth by inducing PANoptosis in DLBCL cells." (PMID 37781035, 2023). "STING activation responds to SAMHD1 deficiency-induced DNA damage and further induces PANoptosis to suppress tumor growth." (PMID 37781035, 2023). "In summary, SAMHD1’s potential role as a tumor suppressor is underlined by various studies and our own analyses that show its downregulation or deregulation through mutations in malignant diseases." (PMID 34480199, 2022). "In vivo, SAMHD1 deficiency and radiotherapy cooperated to inhibit tumor growth and increased M1 macrophages and CD8+ T cell infiltration." (PMID 36578072, 2022). "Radiotherapy causes DNA damage and activates anti-tumor immunity, and SAMHD1 participates in DNA damage repair and innate immune responses." (PMID 36578072, 2022). "Here, we found that SAMHD1 expression was significantly associated with tumor histology and tumor grade, being poorly differentiated high-grade tumors those presenting the highest proportion of SAMHD1 positive cases." (PMID 35158911, 2022). "In vitro evaluation of its underlying mechanism revealed that SAMHD1 KO cells presented enhanced susceptibility to DNA damage and subsequent induction of apoptosis of tumor cells." (PMID 35158911, 2022). "Inactivating mutations in SAMHD1 can promote tumor cell survival as they lead to increased dNTP levels." (PMID 29352181, 2018). "Furthermore, depletion of tumor-associated SAMHD1 triggered innate immune responses and improved tumor cell killing by natural killer (NK) cells." (PMID 41392286, 2025). "Thus, we screened FDA-approved small-molecule drugs covering multiple cellular signaling pathways for their abilities to reduce tumor-associated SAMHD1." (PMID 41392286, 2025). "Our data suggest that the phosphorylation status of SAMHD1 may be a key factor in selective sensitivity of tumor-associated SAMHD1 compared to SAMHD1 proteins in normal cells when treated with HSP90 inhibitors." (PMID 41392286, 2025). "Moreover, selective depletion of tumor-associated SAMHD1 activated innate immune responses, leading to enhanced tumor cell killing by immune cells." (PMID 41392286, 2025). "Accordingly, SAMHD1 expression was significantly associated with tumor grade, being poorly differentiated, high-grade tumors those with the highest proportion of SAMHD1 positive cases and showing significantly higher levels of the cell proliferation marker Ki67." (PMID 37667113, 2024). "Next, we sought to explore the mechanism by which SAMHD1 deficiency suppressed DLBCL tumor growth." (PMID 37781035, 2023). "SAMHD1 deficiency markedly reduced tumor size and suppressed tumor growth." (PMID 37781035, 2023). "In summary, it will be important to address how acquired SAMHD1 mutations provide an advantage for cancerous cells and whether differences between tumor types are observable (for instance, hematological malignancies vs solid tumors)." (PMID 34480199, 2022). "SAMHD1 silencing causes homologous recombination deficiency which may sensitize tumor cells to radiotherapy." (PMID 36578072, 2022). "The dNTP-degrading enzyme SAMHD1 protects against cytotoxic dGTP buildup upon deoxyguanosine supplementation: SAMHD1-deficient tumour cells are sensitive to dGTP accumulation caused by deoxyguanosine supplementation and purine nucleoside phosphorylase inhibition." (PMID 35927450, 2022).